MDN1 (midasin AAA ATPase 1)
Description:
Nuclear chaperone required for maturation and nuclear export of pre-60S ribosome subunits. Functions at successive maturation steps to remove ribosomal factors at critical transition points, first driving the exit of early pre-60S particles from the nucleolus and then driving late pre-60S particles from the nucleus (By similarity). At an early stage in 60S maturation, mediates the dissociation of the PeBoW complex (PES1-BOP1-WDR12) from early pre-60S particles, rendering them competent for export from the nucleolus to the nucleoplasm (By similarity). Subsequently recruited to the nucleoplasmic particles through interaction with SUMO-conjugated PELP1 complex. This binding is only possible if the 5S RNP at the central protuberance has undergone the rotation to complete its maturation (By similarity).
Synonyms: KIAA0301; Rea1
Tractability: PROTAC: ubiquitination databases record sites on it; its protein half-life has been measured; a small molecule that binds it is known.
Gene: Protein-coding gene on chromosome 6 (89,642,498 to 89,819,794, reverse strand). Ensembl gene ENSG00000112159.
Subcellular location: Nucleus, nucleolus; Nucleus, nucleoplasm; Cytoplasm
Subcellular location (Human Protein Atlas): Cytosol; Nucleoli; Intermediate filaments; Nucleoplasm
Gene Ontology:
Molecular function: protein binding; ATP hydrolysis activity; ATP binding
Biological process: ribosomal large subunit assembly; cleavage in ITS2 between 5.8S rRNA and LSU-rRNA of tricistronic rRNA transcript (SSU-rRNA, 5.8S rRNA, LSU-rRNA)
Cellular component: cytoplasm; membrane; nucleolus; nucleus; rixosome complex; nucleoplasm
Genetic constraint (gnomAD): Loss-of-function variants: 233 observed, 622.9 expected, observed/expected ratio (o/e) 0.37, 90% interval 0.34 to 0.42. The upper end of that interval is the gene's LOEUF score, 0.42, which puts it in group 1 of 6, group 1 being the genes least tolerant of losing a copy. Missense variants: 5,532 observed, 6,615.8 expected, observed/expected ratio (o/e) 0.84, 90% interval 0.82 to 0.86. Synonymous variants: 2,241 observed, 2,441.1 expected, observed/expected ratio (o/e) 0.92, 90% interval 0.89 to 0.95.
Homologues: Orthologues: chimpanzee MDN1 (99% identical), macaque MDN1 (98% identical), dog MDN1 (90% identical), pig MDN1 (89% identical), rabbit MDN1 (88% identical), guinea pig MDN1 (86% identical), mouse Mdn1 (82% identical), rat Mdn1 (82% identical), tropical clawed frog mdn1 (62% identical), zebrafish mdn1 (56% identical), Drosophila melanogaster CG13185 (32% identical), Caenorhabditis elegans F55F10.1 (23% identical). Paralogues in human: TCHHL1 (4% identical), IWS1 (3% identical), SAMD15 (3% identical).
Diseases named in the same sentence as MDN1 in open-access papers:
MDN1 is named in the same sentence as 13 diseases in open-access papers, as found by Europe PMC text mining. Sharing a sentence is not in itself a finding about the gene and the disease. The quoted sentences say what the papers report.
breast carcinoma (2 papers, 2022 to 2024). "MDN1 mutation is associated with a high tumour mutation burden and unfavourable prognosis in breast cancer." (PMID 39538416, 2024).
colorectal cancer (2 papers, 2022 to 2024). A primary or metastatic malignant neoplasm that affects the colon or rectum. "Mutations in MDN1, which was downregulated in association with colorectal cancer here, have been shown to correlate with elevated tumor mutation rates in breast and colorectal cancers." (PMID 39227979, 2024). "As an important protein enzyme affecting the process of ribosome synthesis, MDN1 has been found to be mutated in a few cancers, such as colorectal cancer and SCC of the skin, and may act as a driver gene to promote the occurrence and development of cancer." (PMID 35386280, 2022).
B-cell lymphoma (1 paper, 2021). "For B-cell lymphoma only three genes are found in cosmic (CD22, MDN1, and PlCG2) and three genes (CD22, PTPN6, PLCG2) are oncogenes." (PMID 34570764, 2021).
brain cancer (1 paper, 2022). A primary or metastatic malignant neoplasm affecting the brain. "Additionally, TTI2 in prostate, APC in breast, MAD2L2 in pan-cancer, HERC2 in prostate, and MDN1 in brain cancer associated with the mutation component dMMRICA." (PMID 35764656, 2022).
colon cancer (1 paper, 2023). "To further test the applicability of the CGE method for studying precise mutations in diploid cells, we performed ChIP using anti-MYC and anti-H3K27ac antibodies after precision editing of the MDN1 locus in HCT116 colon cancer cells." (PMID 36163549, 2023).
endometrial cancer (1 paper, 2024). Primary or metastatic malignant neoplasm involving the endometrium (mucous membrane that lines the endometrial cavity). "Gene loci associated with endometrial cancer, including BPTF and MDN1, were upregulated in uterine epithelial cells after estrogen treatment." (PMID 39872660, 2024).
epilepsy (1 paper, 2025). A brain disorder characterized by episodes of abnormally increased neuronal discharge resulting in transient episodes of sensory or motor neurological dysfunction, or psychic dysfunction. "These variants were identified in patients with FS or epilepsy secondary to brain damage, suggesting MDN1 as a potential susceptibility gene for epilepsy." (PMID 40217384, 2025). "Compound heterozygous MDN1 variants including eight missenses and one splicing variant were identified in five unrelated individuals with FS or secondary epilepsy." (PMID 40217384, 2025). "This study suggests that MDN1 is potentially a susceptibility gene for epilepsy." (PMID 40217384, 2025). "In conclusion, this study suggests that MDN1 variants contribute to the susceptibility to epilepsy." (PMID 40217384, 2025). "This study aims to explore the association between MDN1 variants and epilepsy." (PMID 40217384, 2025). "This study suggested that MDN1 may be a susceptibility gene for epilepsy." (PMID 40217384, 2025). "The molecular subregional implications and hydrophobicity alterations of MDN1 potentially play a role in the pathogenesis of epilepsy." (PMID 40217384, 2025). "However, MDN1 variants have not been previously reported in patients with epilepsy." (PMID 40217384, 2025).
sarcoma (1 paper, 2022). A usually aggressive malignant neoplasm of the soft tissue or bone. "Although MDN1, HMCN1 and LAMA2 mutation were universally present and significantly different among the three groups, up until now there was no study had reported the mutation of these three genes in any kind of sarcoma." (PMID 36153483, 2022).
type 2 diabetes (1 paper, 2020). "We found that DNA methylation at one CpG, cg1680945 (MDN1), which was associated with adult type 2 diabetes in a previous study, was also associated with maternal early-pregnancy insulin concentrations." (PMID 32894192, 2020).
tumor (7 papers, 2017 to 2025). "To analyze the relationship between MDN1 gene mutation and immune cell infiltration in the tumor microenvironment of the patients, we calculated the percentage of immune cell infiltration in the tumor microenvironment using the CIBERSORT algorithm." (PMID 35386280, 2022). "Second, despite one tumor “TCGA-AC-A23H” had several more mutations relative to the rest of the samples in the MDN1-MUT cohort." (PMID 35386280, 2022). "MDN1 is also a tumor suppresser gene, which had higher mutation rate and elevated expression in the no metastasis group in the METABRIC cohort." (PMID 35111673, 2021). "Moreover, a mutation in Mitochondrial Dysfunctional 1 (MDN1) was enriched in drug metabolism cytochrome P450 pathways and associated with a high tumor mutational burden (TMB) and poorer prognosis in patients with BRCA." (PMID 41278297, 2025). "Only a few studies have reported that the MDN1 mutation exists in carcinomas and may be associated with tumor oncogenesis and prognosis." (PMID 35386280, 2022). "The clinical attributes of BRCA based on the MDN1 mutation status were assessed by comparing TMB and tumor infiltrating immune cells." (PMID 35386280, 2022). "However, the associations of MDN1 mutation with tumor mutation burden (TMB) and prognosis of BRCA have not been investigated." (PMID 35386280, 2022).
cancer (5 papers, 2017 to 2024). A tumor composed of atypical neoplastic, often pleomorphic cells that invade other tissues.
MDN1 also shares sentences with these, for which no sentence is quoted: infection (2 papers); prostate carcinoma (1).